GLI2 (GLI family zinc finger 2)
Diseases named in the same sentence as GLI2 in open-access papers (continued):
Sharing a sentence is not in itself a finding about the gene and the disease.
skin tumors (10 papers, 2013 to 2025). "For example, mice overexpressing Gli1 in skin epidermis (K5-Gli1) develop several types of skin tumors, primarily hair follicle-derived tumors and BCCs, whereas Gli2 overexpression (K5-Gli2) only causes the formation of BCCs." (PMID 31438551, 2019). "In tumor cell lines, bone tumors displayed the highest expression of both GLI1 and GLI2, whereas skin tumor cell lines exhibited the greatest expression of GLI3." (PMID 38498906, 2024). "Gli2 transgenic mice have developed BCC-like skin tumors and keratinizing jaw cysts, indicating that Gli2 overexpression is sufficient for jaw cyst formation." (PMID 23951062, 2013). "Here, we report that Src‐associated substrate during mitosis of 68 kDa (Sam68), an early signaling molecule in DDR, is elevated in skin tumor tissues derived from NMSC patients and skin lesions from Gli2‐transgenic mice." (PMID 31436046, 2019). "Here, we report that Sam68, an early signaling molecule in DDR, is elevated in skin tumor tissues derived from NMSC patients and skin lesions from Gli2‐transgenic mice." (PMID 31436046, 2019). "Expression of intermediate filament protein keratin K17 is found to be upregulated in skin tumors and is responsible for induction of AIRE in tumor keratinocytes which is required for the onset of Gli-2 mediated skin tumorigenesis." (PMID 29795364, 2018). "Nevertheless, investigations have revealed that the Gli2 protein could produce skin cancers even in the absence of primary cilia, thereby providing evidence that the Gli protein did not need cilia to reach the nucleus." (PMID 37851362, 2023).
Obesity (9 papers, 2013 to 2025). Accumulation of substantial excess body fat. "Thus, like SmoM2, postnatal activation of Gli2 in the adipocyte lineage suppresses obesity and metabolic dysfunction caused by a high fat diet." (PMID 29205155, 2017). "Here by inducing expression of constitutively active Smoothened (SmoM2) or Gli2 (ΔNGli2) in the adipocyte lineage of postnatal mice, we show that targeted activation of Hh signaling suppresses high-fat-diet-induced obesity and improves whole-body glucose tolerance and insulin sensitivity." (PMID 29205155, 2017). "From this analysis, methylation data (β values) of cancer-related genes previously identified in the DNA of leukocytes from patients with obesity after following a VLCKD to lose weight were isolated (CCND1, MAPK10, GLI2, LAMC3 and CTNNA2)." (PMID 40140215, 2025). "For instance, obesity downregulates SHH signaling, including the expression of GLI1, GLI2, and GLI3." (PMID 31316554, 2019). "Genetic ablation of GLI2 or SMO in mice implies defective Hh signaling pathway that results in obesity, but, physiologically, whether dysregulated Hh signaling contributes to hypertrophic obesity warrants further investigation, in particular the missing link with ASCs and preadipocyte commitment." (PMID 36831329, 2023). "CNTNAP2, GLI2, DPT (dermatopontin), AEBP1, ITIH5, CXCL11, GDNF (glial cell derived neurotrophic factor), MCHR1, FLT3, ELANE (elastase, neutrophil expressed), OSMR (oncostatin M receptor) and IL15RA are involved in development of obesity, but these genes might be key for progression of HF." (PMID 34218797, 2021).
bladder cancer (8 papers, 2015 to 2025). "To explore the association of ROC1, SUFU, and Gli2 expression with the tumor clinicopathological grade, we analyzed their expression immunohistochemically in human bladder cancer tissues." (PMID 33499884, 2021). "From a pan-cancer large-scale analysis 15, we could further extrapolate that GLI2 is most significantly associated with TGFβ3 in bladder cancer patients, laying the foundation for this study." (PMID 40027190, 2025). "In addition, our current ex vivo data further revealed an association between ROC1 expression and the hedgehog pathway proteins, i.e., ROC1 expression was inversely associated with SUFU (P < 0.001) but positively associated with Gli2 expression (P < 0.001) in bladder cancer tissues." (PMID 33499884, 2021). "We started with a bioinformatics approach and identified a novel gene signature, TGFβ3/GLI2/YAP1 (the TGY) signature, significantly associated with immune evasion and therapy resistance in bladder cancer." (PMID 40027190, 2025). "Collectively, the bioinformatics analysis identified TGFβ3/GLI2/YAP1 as a potential target gene signature (TGY signature) in bladder cancer." (PMID 40027190, 2025). "In summary, our study identifies a unique TGFβ3/GLI2/YAP1 (the TGY signature) that is not only elevated in bladder cancer cells but also plays a crucial role in CAF transformation and function." (PMID 40027190, 2025). "In conclusion, iG2 is a novel Gli2 inhibitor that is potential to be used to target self‐renewal of CSCs in bladder cancer patients." (PMID 27465044, 2016). "The iG2 can strongly downregulated the expression of Gli1, Gli2, and downstream Jag2 genes in bladder cancer cells." (PMID 27465044, 2016). "The result showed that iG2 strongly inhibited the expression of Hh pathway transcriptional factors Gli1 and Gli2, as well as the downstream protein Jag2 in primary bladder cancer cells." (PMID 27465044, 2016). "Here, we isolated a novel Hh inhibitor iG2 from streptomyces roseofulvus, which dramatically blocked the activation of Gli2 in bladder cancer cells." (PMID 27465044, 2016). "Subsequent characterization demonstrated that iG2 inhibited not only the UTR‐mediated reporter expression but also endogenous Gli2 expression in human bladder cancer T24." (PMID 27465044, 2016). "Here, we separated a novel hedgehog (Hh) inhibitor, iG2, from streptomyces roseofulvus, which dramatically blocked the activation of Gli2 in bladder cancer cells." (PMID 27465044, 2016). "In this study, we identified a novel Gli2 inhibitor iG2 from streptomyces roseofulvus, which dramatically blocked tumorigenesis of bladder cancer cells." (PMID 27465044, 2016). "To explore the possible downstream signaling pathway activated by iG2, we found that iG2 dramatically down‐regulated Gli2 of Hh pathway in bladder cancer cells." (PMID 27465044, 2016). "In a series of bladder cancer cell lines, it was found that Hh-independent GLI2 expression and function contributes to invasiveness." (PMID 26343727, 2015). "Notably, the GLI2 demonstrated a higher correlation (cor = 0.61, p<0.001) with TGFβ3 in bladder cancer when compared to other cancer type." (PMID 40027190, 2025). "In bladder cancer, Gli2 inhibition by GANT61 has been shown to reduce cell invasiveness." (PMID 27465044, 2016). "Collectively, our bioinformatics results strongly support that the TGFΒ3/GLI2/YAP1 expression level is significantly associated with tumor-infiltrating CAFs, T cell desertion, and immunosuppressive phenotypes and is resistant to immunotherapy in bladder cancer." (PMID 40027190, 2025). "In general, Gli2 could play a more important role in bladder cancer." (PMID 33499884, 2021). "We then divided their expression levels into two categories (low vs. high) and found that ROC1 and Gli2 expression was low, but SUFU expression was high in the low-grade bladder cancer tissues compared with those in high-grade tumors." (PMID 33499884, 2021).
bladder cancer (continued). "Collectively, bladder cancer tissues with low ROC1 expression had high SUFU and low Gli2 expression levels." (PMID 33499884, 2021). "In the current study, we demonstrated that knockdown of ROC1 expression inhibited Gli2 expression but not Gli1 expression, whereas ROC1 overexpression promoted Gli2 expression in bladder cancer cells." (PMID 33499884, 2021). "Future research is needed to evaluate the exact mechanism of how NRP2 and GLI2 communicate bidirectionally, how NRP2 modulates SPP1 transcription, and what implications this will have for development and progression of other cancer entities apart from bladder carcinoma." (PMID 32038994, 2019). "The authors suggested that non-canonical GLI2 activity may be attributed to RAS and TGF-β, both of these pathways being critical for bladder cancer development." (PMID 26343727, 2015).
lung adenocarcinoma (8 papers, 2014 to 2026). A carcinoma that arises from the lung and is characterized by the presence of malignant glandular epithelial cells. "For instance, CRKL was identified as a transcriptional target of Hh-GLI2 pathway in lung adenocarcinoma and played an essential role in GLI2-driven cell proliferation and migration." (PMID 40045194, 2025). "In this study we show that lung adenocarcinoma specimens from two cohorts of patients, Gli1 and Gli2 are inversely correlated with the cell adhesions protein E-Cadherin, suggesting that high levels of Gli are associated with markers of EMT." (PMID 27533453, 2016). "We found that GLI1, GLI2, and GLI3 mRNA were expressed in almost all advanced stage lung adenocarcinoma tissue samples, and strong correlation was observed between GLI1 and GLI3 mRNA expression." (PMID 25103784, 2014). "The levels of GLI1, GLI2, and GLI3 mRNA expression were measured by quantitative real-time polymerase chain reaction in surgically obtained tissue samples from stage II-IV lung adenocarcinoma patients (n = 102)." (PMID 25103784, 2014). "From our research, no relation between GLI2 mRNA expression and GLI1 mRNA level, GLI3 mRNA level, or patient survival was detected, thus, the role of GLI2 in the pathogenesis of lung adenocarcinoma is still unclear." (PMID 25103784, 2014).
hypospadias (7 papers, 2016 to 2024). Hypospadias is the displacement of the urethral meatus on the ventrum of the penis. "Therefore, the alteration of Gli2 may represent a regulatory or compensatory mechanism in this disease, underlying the mechanism of hypospadias." (PMID 34867780, 2021). "Patient 3 presented two variants in two genes: GLI2 (associated to gonadal/genital anomalies) and RECQL4 (associated to syndromic hypospadias)." (PMID 31555317, 2019). "Among the eighteen genes, four have been previously identified in patients with hypospadias (CYP1A1, FLNA, GLI3, and GLI2), three have been reported to be associated with cryptorchidism (FLNA, RET, and PTPN11), and one has been identified in patients with micropenis (EVC)." (PMID 33424767, 2020).
ovarian tumors (6 papers, 2014 to 2025). "A previous study reported that GLI1 and GLI2 mRNA levels, indicators of active HH signaling, were significantly higher in cancer cells isolated from persistent/chemoresistant ovarian tumors than those isolated from matched primary tumors." (PMID 40565349, 2025). "In a previous study, we reported that GLI1 and GLI2 mRNA levels, indicators of hedgehog signaling, were significantly higher in cancer cells isolated from persistent/chemoresistant ovarian tumors compared to those isolated from matched primary tumors." (PMID 25216523, 2014). "Further histochemical and molecular analyses provided evidence of overactivation of TGFBR1 in the granulosa cell compartment during ovarian pathogenesis in TGFBR1-CAG9Cre mice, along with upregulation of Gli1 and Gli2 and downregulation of Tgfbr3 in ovarian tumor tissues." (PMID 29221447, 2017). "Second, ovarian tumors in TGFBR1-CAAcre mice had higher levels of Gli1 and Gli2 mRNAs." (PMID 27344183, 2016).
acute myeloid leukemia (5 papers, 2014 to 2022). Acute myeloid leukemia (AML) is a group of neoplasms arising from precursor cells committed to the myeloid cell-line differentiation. "Acute myeloid leukemia (AML) has been one of the most promising targets of HH inhibition therapy, either with Smo inhibitors or with further downstream inhibitors of GLI1 and GLI2 activators." (PMID 36091167, 2022). "Thus, Gli2 may be an alternative target for the treatment of acute myeloid leukemia (AML)." (PMID 25009639, 2014).
asthma (4 papers, 2013 to 2022). "If the interaction is genuine, it could provide new insight into the biological role of ADAM33 or its neighboring genes in asthma susceptibility, and may also emphasize GLI2 as a new gene of investigation for asthma." (PMID 27387956, 2016). "Transcriptional activation of GLI2 depends on SMAD3, which was one of the top asthma-associated genes in the original GABRIEL study." (PMID 27387956, 2016). "The other gene in the identified interaction, GLI2, has been reported to be involved in T-cell function and TGFβ expression, which are both well-known components of asthma pathogenesis." (PMID 27387956, 2016). "Thus, it is highly plausible that GLI2 has biological relevance in asthma." (PMID 27387956, 2016). "In addition, rs11684871 is located in or near GLI2, which may have biologically relevant roles in asthma." (PMID 27387956, 2016). "Collectively, our primary cell data showed an upregulation of SHH, SMO, GLI2 and PTCH1 gene expression with epithelial differentiation independent of a diagnosis of asthma." (PMID 36230980, 2022).
basal cell carcinomas of the skin (4 papers, 2014 to 2023). "Conversely, the overexpression of mouse and human GLI2 under control of the bovine K5 promoter (K5-Gli2N), which is active in keratinocytes of epidermal basal layer, leads to basal cell carcinomas of the skin." (PMID 37608807, 2023). "While GLI1 is itself a GLI1 regulatory target, in basal cell skin carcinoma cells, activation of GLI2 by GLI1 is indirect, and perhaps context dependent." (PMID 25252859, 2014).
cleft palate (4 papers, 2016 to 2025). Cleft palate is a fissure type embryopathy that affects the soft and hard palate to varying degrees. "In addition, mutant mice deficient for GLI2 exhibit severe skeletal abnormalities, including cleft palate." (PMID 31386309, 2019). "Disruption of the function of Shh, Smo, or the transcriptional effectors Gli2 or Gli3, during palatal development each causes cleft palate in the mutant mice, indicating that Shh signaling regulates palate development through Gli mediated transcriptional regulation." (PMID 26745863, 2016). "Additionally, of note, both Subjects 7 and 11 had PDVs in genes included on the testing panel for cleft palate—GLI2 and FOXE1, respectively— and had craniofacial malformations involving the mouth." (PMID 33562221, 2021).
diabetes (4 papers, 2022 to 2024). "Although both parents harbor the c.C4661T variant in GLI2, only the father developed diabetes." (PMID 38509065, 2024). "Here, we applied CRISPR-Cas9 gene editing on human iPSCs to study a heterozygous missense variant of GLI2 gene (GLI2P1554L) identified in a child with diabetes of unknown origin and family members." (PMID 38509065, 2024). "Collectively, our findings underscore an essential role for GLI2 in human endocrine development and identify a gene variant that may lead to diabetes." (PMID 38509065, 2024). "In a consanguineous family with diabetes of unknown etiology, we identified an uncharacterized heterozygous GLI2 missense variant (hg38 chr2:120990575; NM_001371271.1:c.4661 C > T; p.P1554L; rs767802807)." (PMID 38509065, 2024). "Our findings show that GLI2 plays an essential role in human endocrine cell development and identify a previously unknown variant that eventually leads to diabetes." (PMID 38509065, 2024). "Additional insights indicated that KIAA0753 effectively restored osteoblast differentiation by directly interacting with SHH, OCN and Gli2, thereby activating the Hedgehog signalling pathway and mitigating the ubiquitination of Gli2 in diabetes." (PMID 39245790, 2024). "GLI2 is one of the abnormally expressed transcription factors in models of diabetes and its complications." (PMID 38385859, 2024). "However, neither mutations in GLI2 nor Hedgehog dysregulation have been reported as cause or predisposition to diabetes." (PMID 38509065, 2024). "So far, mutations in GLI2 have not been associated with diabetes in publicly available databases." (PMID 38509065, 2024). "In this study, we confirmed that impairment of primary cilia induced by diabetes directly led to inhibition of Hedgehog signaling, characterized by reduced SHH/Gli2 expression and increased Ptch1/Sufu expression." (PMID 36552853, 2022).
holoprosencephaly 9 (4 papers, 2023 to 2025). Any holoprosencephaly in which the cause of the disease is a mutation in the GLI2 gene. "Furthermore, mutations or dysregulation of GLI2 are linked to multiple human developmental diseases, such as Culler-Jones syndrome (OMIM #615849), characterized by hypopituitarism, abnormalities of the external genitalia, and postaxial polydactyly and holoprosencephaly 9 (HPE9, OMIM #610829)." (PMID 38884091, 2024).
renal cell carcinoma (4 papers, 2017 to 2024). "Enhanced GLI2 transcriptional activity promotes tumor angiogenesis and cancer stemness in renal cell carcinoma." (PMID 38498906, 2024). "PI3K/AKT can activate GLI1 and GLI2 through the non-classical Hh signaling pathway to enhance renal cell carcinoma's proliferation and clonogenic ability." (PMID 38498906, 2024). "Another group could demonstrate a non-canonical activation of GLI1 in esophageal adenocarcinoma via TNF-α and subsequently mTOR/S6K1 while Zhou and colleagues could recently show that GLI1 and GLI2 are non-canonically activated via PI3K/AKT in human renal cell carcinoma." (PMID 28418873, 2017).
squamous cell carcinoma (4 papers, 2016 to 2024). A carcinoma arising from squamous epithelial cells. "In squamous cell carcinoma, inhibition of the ULK3 gene inhibits fibroblast effector gene expression as well as GLI2 activation, while inhibiting the growth-enhancing and oncogenic properties of these cells of neighboring cancer cells." (PMID 34168974, 2021). "We analyzed additional 9 cases of mandibular squamous cell carcinoma with invasive bone destruction and observed (i) intense SHH immunoreactivity in tumor cells, (ii) intense Patched and Gli-2 immunoreactivity in osteoclasts and progenitor cells in all cases (not shown)." (PMID 27007126, 2016).
Anosmia (3 papers, 2021 to 2025). An inability to perceive odors. "A previously reported child with anosmia, partial GH deficiency, hypogonadotropic hypogonadism, and low bone mass carried a different missense variant in GLI2 (p.Tyr176Cys), further illustrating this genotypic and phenotypic heterogeneity." (PMID 40908550, 2025). "Similarly, Gli2/Gli3 mutants, which model disrupted GnRH neuronal migration analogous to Kallmann syndrome, often exhibit early lethality or anosmia that prevent behavioral assessment into adulthood." (PMID 41357796, 2025). "As far as is known, this is the first report evidencing digenic mutations in patients with KS and P/LP variants in PROKR2 and GLI2 (PROKR2: p.R85H and GLI2: p.A185S) genes (proband 30 with anosmia, absence of puberty, and micropenis)." (PMID 34198905, 2021).
brain tumors (3 papers, 2014 to 2023). "In contrast, ablation of PC enhances brain tumor growth induced by activated GLI2." (PMID 27793025, 2016).